CFTR (CF transmembrane conductance regulator)
Diseases named in the same sentence as CFTR in open-access papers (continued):
Sharing a sentence is not in itself a finding about the gene and the disease.
cystic fibrosis (continued). "Mutation in the cystic fibrosis gene is associated with idiopathic chronic pancreatitis when present in heterozygous state in association with other CFTR polymorphism." (PMID 24616641, 2014). "Located on chromosome 7q31.2, the CFTR gene contains 27 exons and 1945 polymorphisms according to the Cystic Fibrosis Variations Database." (PMID 25170420, 2014). "Defective processing and functioning of this protein caused by mutations in the CFTR gene results in loss of ionic balance, defective mucus clearance, increased proliferation of biofilms and inflammation of human airways observed in cystic fibrosis patients." (PMID 25120007, 2014). "One example of a glycoprotein that accumulates in cytoplasmic aggregates is the cystic fibrosis transmembrane conductance regulator (CFTR), the glycoprotein whose mutant forms cause cystic fibrosis." (PMID 24609034, 2014). "Cystic fibrosis, the most common autosomal recessive disease in Caucasians, is due to mutations in the CFTR gene." (PMID 24586461, 2014). "If the gene responsible for the CFTR channel is mutated severely, the result is cystic fibrosis, a hereditary disorder in which the patient develops thick mucus, especially in the lungs, as well as scarring (fibrosis) in the pancreas." (PMID 25033378, 2014). "Cystic fibrosis is caused by mutations in the cystic fibrosis transmembrane conductance regulator (CFTR)." (PMID 24416359, 2014). "Loss-of-function mutations in CFTR are responsible for the fatal disease cystic fibrosis, of which the most studied is a deletion of a phenylalanine at position 508 (∆F508) that abolishes CFTR folding and plasma membrane expression." (PMID 25036888, 2014). "P. aeruginosa is a common pathogen of individuals with cystic fibrosis, a genetic disease that is caused by a mutation in the gene coding for the CFTR ion transporter and strongly associated with chronic, recalcitrant lung infections." (PMID 25340349, 2014). "Cystic fibrosis is caused by mutations in the CFTR gene (cystic fibrosis transmembrane regulator), detected for the first time in 1989." (PMID 25304080, 2014). "Cystic fibrosis, an autosomal recessive disease caused by mutations in the CF transmembrane conductance regulator (CFTR) gene, is an inherited, life-limiting condition." (PMID 24438707, 2014). "Genetic variants in CFTR cause cystic fibrosis, a Mendelian condition that is more prevalent in Caucasians." (PMID 24555763, 2014). "Our results show that double heterozygosity of cystic fibrosis and CFTR-related disorder (CFTR-RD) mutations are found in a high percentage (22.7%) of infertile men with obstructive azoospermia, but not in other studied groups of infertile men." (PMID 25386751, 2014). "Mutations in CFTR gene are causing cystic fibrosis or related phenotypes, named CFTR-related disorders (CFTR-RD)." (PMID 25386751, 2014). "Cystic fibrosis is caused by the functional deficiency of a cAMP-activated plasma membrane chloride channel known as the cystic fibrosis transmembrane conductance regulator (CFTR)." (PMID 24970227, 2014). "Patients with cystic fibrosis harbour mutations in the CFTR chloride channel and often develop diabetes for reasons that are poorly understood." (PMID 25025956, 2014). "We aimed at assessing the association of this polymorphism with disease severity in a group of Cystic Fibrosis patients homozygous for F508del CFTR gene mutation." (PMID 25503271, 2014). "The deltaF508CFTR mutant - the most predominant CFTR mutation in cystic fibrosis patients - is characterized by a misfolded CFTR protein which is rapidly degraded by the proteasome and thus fails to translocate to the plasma membrane." (PMID 26567105, 2014). "Cystic fibrosis is an autosomal recessive disease caused by mutations in the cystic fibrosis transmembrane conductance regulator (CFTR) gene, which encodes a chloride channel expressed at the apical surface of secretory epithelia." (PMID 24901709, 2014).
cystic fibrosis (continued). "Cystic fibrosis is the most common lethal, heritable disease in the US and results from mutations in the gene encoding the CF transmembrane conductance regulator." (PMID 24763694, 2014). "Cystic fibrosis is a lethal genetic disorder resulting from a mutation of the CFTR gene coding for a Cl− channel normally localized in the apical membrane of epithelial cells." (PMID 25107986, 2014). "Cystic fibrosis is a genetic disease caused by mutations in the CFTR (CF Transmembrane conductance Regulator) gene, encoding a plasma-membrane chloride channel." (PMID 24586495, 2014). "With regard to the 76 patients with cystic fibrosis and a positive sweat test, all have two CFTR-mutated genes." (PMID 25304080, 2014). "A canonical example is provided by the disease cystic fibrosis, which is caused by mutations in cystic fibrosis transmembrane conductance regulator (CFTR), a plasma membrane chloride channel." (PMID 24396149, 2014). "More than 1,900 mutations of CFTR responsible for the disease have now been listed by the Cystic Fibrosis Genetic Analysis Consortium." (PMID 24586495, 2014). "Cystic fibrosis transmembrane conductance regulator (CFTR) gene mutation analysis has been implemented for Cystic Fibrosis carrier screening, and molecular diagnosis of CF and congenital bilateral absence of the vas deferens (CBAVD)." (PMID 25071991, 2014). "Cystic fibrosis is a monogenic disease caused by mutations in the CFTR gene and is characterized by mucus airway obstruction, neutrophil-dominated airway inflammation, and bacterial infection that lead to massive proinflammatory phenotype in the lung." (PMID 24991086, 2014). "It has recently been argued that mucus in cystic fibrosis lungs is excessively viscous due to loss of CFTR dependent bicarbonate secretion, and that the newly formed mucus gel fails to properly expand." (PMID 24608905, 2014). "Cystic fibrosis is a genetic disease caused by mutations in the cystic fibrosis transmembrane conductance regulator (CFTR)." (PMID 25007800, 2014). "Cystic Fibrosis is a lethal genetic disease in which mutations in the CF transmembrane Conductance Regulator (CFTR) gene result in defective function and/or processing of the mutant protein CFTR." (PMID 24926292, 2014). "The CFTR molecule has been intensely studied because mutations in the CFTR gene are associated with cystic fibrosis (CF, OMIM #219700), the most common life-threatening genetic disorder among populations of Northern European ancestry." (PMID 25033378, 2014). "Cystic fibrosis is an autosomal recessive syndrome usually caused by inheriting two CFTR mutations that eliminate effective chloride conductance (CFTRCF)." (PMID 25033378, 2014). "Cystic fibrosis is a genetically determined condition which is caused due to a mutation in the CFTR gene." (PMID 24616813, 2014). "The F508del-CFTR mutation, responsible for Cystic Fibrosis, leads to the retention of the protein in the endoplasmic reticulum (ER)." (PMID 24586495, 2014). "The most common causative mutation in cystic fibrosis is deletion of a phenylalanine residue at position 508 (ΔF508) in CFTR." (PMID 24396149, 2014). "The majority of reported cases of TRPA have associated cystic fibrosis, the δF508 CFTR (cystic fibrosis transmembrane conductance regulator) mutation being thought to be a predisposing factor for this disease." (PMID 24653762, 2014). "Cystic fibrosis presents with broad phenotypic variability, even in patients with identical mutations in the causative gene, cystic fibrosis transmembrane conductance regulator (CFTR)." (PMID 24593045, 2014). "Cystic fibrosis is caused by mutations in the cystic fibrosis transmembrane conductance regulator (CFTR) gene and is found with a prevalence of 1 in 2,500–3,500 Caucasian newborns." (PMID 25085879, 2014). "Cystic Fibrosis, caused by mutations in the cystic fibrosis transmembrane conductance regulator (CFTR) protein, is a common lethal genetic disease among Caucasians." (PMID 24716008, 2014).
cystic fibrosis (continued). "Cystic fibrosis is caused by defects in the gene for CFTR, an integral membrane protein important for electrolyte/fluid transport." (PMID 24204751, 2013). "Cystic fibrosis is caused by mutations in CFTR (cystic fibrosis transmembrane conductance regulator), leading to folding and processing defects and to chloride channel gating misfunction." (PMID 24058550, 2013). "Cystic fibrosis is a monogenic disease caused by CFTR gene mutations, with clinical expression similar to complex disease, influenced by genetic and environmental factors." (PMID 23758905, 2013). "Another inherited genetic risk correlates with cystic fibrosis, characterized by mutations in the cystic fibrosis transmembrane conductance regulator (CFTR) gene which is associated with chronic idiopathic pancreatitis." (PMID 24303367, 2013). "Mutations within the gene encoding for the chloride ion channel CFTR results in cystic fibrosis, the most common autosomal recessive genetic disease in the Caucasian population." (PMID 24009583, 2013). "Cystic fibrosis is an autosomal recessively inherited genetic disorder caused by mutations of the CF transmembrane conductance regulator (CFTR) gene." (PMID 23533902, 2013). "The deletion of Phe508 (ΔF508) in the first nucleotide binding domain (NBD1) of CFTR is the most common mutation associated with cystic fibrosis." (PMID 23982976, 2013). "Cystic fibrosis is a genetic disease caused by mutations of cystic fibrosis transmembrane conductance regulator (CFTR) mostly affecting lungs, pancreas, liver, and intestine." (PMID 24967239, 2013). "Screening an ethnically diverse US population sample (N = 364,890) for 87 different CFTR mutations responsible for causing cystic fibrosis yielded a combined carrier frequency of 2.6 %." (PMID 23820649, 2013). "Cystic fibrosis is an autosomal recessive disorder, caused by mutations in the gene that encodes the cystic fibrosis transmembrane conductance regulator (CFTR) protein." (PMID 24056672, 2013). "Cystic fibrosis is caused by mutations in the cystic fibrosis transmembrane conductance regulator (CFTR) gene, which encodes the CFTR ATP-binding cassette protein." (PMID 24040112, 2013). "One prominent example is cystic fibrosis, a common, autosomal recessive disorder due to mutations in a chloride channel known as the CFTR." (PMID 23710194, 2013). "We have identified structurally diverse correctors that restore the trafficking and function of the most common mutation causing cystic fibrosis, F508del-CFTR." (PMID 23316740, 2013). "∆F508 has been the first recognized mutation of the CFTR gene, its prevalence in Caucasian population is estimated at 2.8% and in homozygosis it is responsible for more than 70% of the typical form of cystic fibrosis." (PMID 23883480, 2013). "Since cystic fibrosis carriers (i.e. individuals harbouring a heterozygous severe CFTR allele) correspond to 3% of the general population in many European countries, CFTR mutations represent a major risk factor for ICP." (PMID 23951356, 2013). "If both parents are discovered to be carriers for CFTR mutations, they can opt for adoption or preimplantation genetic diagnosis to reduce their chances of having a child affected with cystic fibrosis." (PMID 25411643, 2013). "This discovery will provide therapeutic avenues for restoring CFTR function to cells affected by the most common cystic fibrosis mutation and mandates miRNA-based research in this field." (PMID 23878802, 2013). "Several databases have reported variants in CFTR including dbSNP, the Cystic Fibrosis Mutation Database (CFMDB), and the Human Gene Mutation Database (HGMD)." (PMID 23343000, 2013). "The genetic disease Cystic Fibrosis results from mutations in CFTR that lead to deficient/dysfunctional CFTR in a variety if epithelial tissues." (PMID 23644890, 2013).
cystic fibrosis (continued). "The pathophysiology of cystic fibrosis lung disease develops as a consequence of mutations in the cystic fibrosis transmembrane conductance regulator (CFTR) protein which is normally expressed in the airways and distal lung." (PMID 23874438, 2013). "Cystic Fibrosis is a life-limiting multisystem disorder arising from abnormal function or complete loss of function of the protein, Cystic Fibrosis Transmembrane Conductance Regulator (CFTR)." (PMID 23617902, 2013). "The aim of our study was therefore to describe prevalence and clinical features in Sicilian patients bearing the p.Leu1077Pro CFTR mutation followed in our Cystic Fibrosis Centre to add new data on this issue." (PMID 24225052, 2013). "Cystic fibrosis is a disease characterized by mutations of the cystic fibrosis transmembrane conductance regulator (CFTR) gene which is associated to intracellular accumulation of misfolded proteins that are supposed to be cleared by autophagy." (PMID 23691501, 2013). "Cystic fibrosis is an autosomal recessive genetic disorder caused by mutations in the cystic fibrosis transmembrane conductance regulator (CFTR)." (PMID 24276381, 2013). "Objective(s): More than 1500 registered mutations in cystic fibrosis transmembrane regulator (CFTR) gene are responsible for dysfunction of an ion channel protein and a wide spectrum of clinical manifestations in patients with cystic fibrosis." (PMID 24106596, 2013). "Cystic fibrosis is caused by mutations of the CFTR gene that encodes a chloride channel predominantly expressed at the apical membrane of epithelial cells." (PMID 23483918, 2013). "Cystic Fibrosis is a lethal genetic disorder which results from a mutation of the gene coding for the Cystic Fibrosis Transmembrane conductance Regulator (CFTR), a cyclic AMP-dependent Cl- channel." (PMID 24688726, 2013). "Cystic fibrosis results from mutations in CFTR that compromise maturation or channel gating and can deleteriously affect many epithelia-lined organs, particularly the lungs, pancreas, and intestines." (PMID 24058550, 2013). "For instance, cystic fibrosis is caused by a variety of different mutations in the chloride transporter encoded by the CFTR gene." (PMID 23504071, 2013). "The Cystic Fibrosis Transmembrane Conductance Regulator, CFTR, is a cAMP-responsive channel for chloride and bicarbonate; mutations in CFTR are responsible for cystic fibrosis." (PMID 24386311, 2013). "Cystic fibrosis is caused by severe dysfunction of cystic fibrosis transmembrane conductance regulator (CFTR), which commonly leads to progressive lung disease and a shortened life." (PMID 22655855, 2012). "Mutations in CFTR can cause cystic fibrosis, a rare disease manifested by thick, sticky mucus and salty sweat, which usually leads to lung transplant or early death." (PMID 22655855, 2012). "The importance of CFTR in cell and organ physiology has been proven by the deleterious consequences of CFTR mutations that lead to Cystic Fibrosis, an autosomal genetic disease." (PMID 22514683, 2012). "Most cases of cystic fibrosis are caused by the deletion of a single phenylalanine residue at position 508 of the cystic fibrosis transmembrane conductance regulator (CFTR)." (PMID 23060796, 2012). "We chose the CFTR-ΔF508 allele causing cystic fibrosis as proof of principle for modeling a human disease-relevant gene interaction network in yeast, because CFTR-ΔF508 is arguably the best-characterized human genetic disease mutation." (PMID 23270647, 2012). "GOPC, a coiled-coil motif and PDZ containing protein, negatively regulates CFTR, mutations in which result in cystic fibrosis." (PMID 23210427, 2012). "The major Cystic Fibrosis mutation, F508del, causes multiple defects in the CFTR protein, leading to its impaired assembly during synthesis and reduced post-translational stability." (PMID 23055971, 2012).
cystic fibrosis (continued). "Since the discovery of the CFTR gene and the mutations that cause cystic fibrosis, attempts at gene correction by CFTR gene transfer to the airways, using both viral and non-viral gene-transfer mechanisms, have been described." (PMID 23029546, 2012). "Most cystic fibrosis is caused by mutations in CFTR that prevent its trafficking from the ER to the plasma membrane and is associated with exaggerated inflammation, altered metabolism, and diminished responses to oxidative stress." (PMID 22988441, 2012). "Cystic fibrosis due to a mutation in the cystic fibrosis transmembrane conductance regulator (CFTR) is associated with focal biliary fibrosis, and the bile duct and ductules are filled with pink and amorphous secretions." (PMID 21994886, 2012). "In this report we considered c.3499+200TA(7_56) and D7S523 polymorphisms on CFTR gene in normal individuals and cystic fibrosis patients in North Iran." (PMID 24551767, 2012). "Cystic fibrosis, an autosomal recessive disorder caused by a mutation in a gene encoding the cystic fibrosis transmembrane conductance regulator (CFTR), remains a leading cause of childhood respiratory morbidity and mortality." (PMID 23029546, 2012). "Cystic fibrosis is an autosomal recessive inherited disease caused by mutation of the cystic fibrosis transmembrane conductance regulator (CFTR) gene, coding for a protein functioning as a transmembrane epithelial chloride channel." (PMID 22309508, 2012). "In cystic fibrosis a single allele of the cystic fibrosis transmembrane conductance regulator (CFTR-ΔF508) accounts for most of the disease." (PMID 23270647, 2012). "The underlying genetic defect in cystic fibrosis is a mutation in the CFTR gene, which encodes a Cl−/bicarbonate ion channel located in the apical surface of airway epithelial cells." (PMID 22912772, 2012). "Cystic fibrosis is caused by the mutation of the gene coding for the Cystic Fibrosis Transmembrane conductance Regulator (CFTR), a cyclic AMP-dependent Cl− channel." (PMID 22662206, 2012). "Cystic fibrosis is an autosomal recessive disease caused by mutations in the cystic fibrosis transmembrane conductance regulator (CFTR), which functions as a chloride ion channel." (PMID 22649552, 2012). "CFTR functions as a chloride channel in human cells and is implicated in the genetic disease cystic fibrosis." (PMID 23284987, 2012). "F508del-CFTR is the most common cystic fibrosis causing mutation, leading to protein misfolding and aberrant trafficking from the ER to Golgi, resulting in a lack of functional expression on the cell surface." (PMID 23055971, 2012). "Cystic fibrosis is the most common severe autosomal recessive genetic disease in Caucasians caused by mutations in the CFTR (cystic fibrosis transmembrane conductance regulator) gene." (PMID 22860029, 2012). "Cystic fibrosis is an autosomal recessive disease caused by mutations in the gene for the cystic fibrosis transmembrane regulator (CFTR) protein." (PMID 22420941, 2012). "The clinical course of cystic fibrosis varies between patients bearing identical CFTR mutations, suggesting the involvement of modifier genes." (PMID 22860029, 2012). "Mutations in the cystic fibrosis transmembrane conductance regulator (CFTR) gene have been implicated in the onset of cystic fibrosis and other clinical respiratory disorders." (PMID 23554779, 2012). "Cystic fibrosis is the most common fatal genetic disease in Caucasians and is caused by mutations of the CF transmembrane conductance regulator (CFTR), a cAMP-stimulated chloride (Cl-) channel." (PMID 21599970, 2011). "Cystic fibrosis pulmonary disease is an autosomal recessive disease caused by defective function of the CFTR protein product, a cAMP-regulated chloride channel." (PMID 21496221, 2011). "F508del-CFTR, the most frequent disease-causing mutation among Caucasian cystic fibrosis patients, has been characterised as a mutant defective in protein folding, processing and trafficking." (PMID 21548936, 2011).